HIF1A (hypoxia inducible factor 1 subunit alpha)
Diseases named in the same sentence as HIF1A in open-access papers (continued):
Sharing a sentence is not in itself a finding about the gene and the disease.
colitis (continued). "Relevance to IBD is suggested by studies in experimental colitis models, and cell lines, which indicate a protective stabilization of HIF1α, attenuating mucosal inflammation and promoting barrier formation." (PMID 34054553, 2021). "HIF-1α along with p-STAT3 enhanced CD11b transcription in a DSS-induced colitis model." (PMID 33808042, 2021). "Furthermore, HIF-1α is induced in the inflamed mucosa of both mouse models of colitis and IBD patients and can improve epithelial barrier function by regulating intestinal trefoil factor (TFF) as well as alleviate many kinds of intestinal inflammation." (PMID 32713852, 2020). "HIF-1α-mediated changes in miRNA expression were found to have a critical effect on the initiation and development of several pathophysiological processes, including ischemic kidney injury, colitis, and gastric cancer." (PMID 32550011, 2020). "However, a HIF-1α knockout in DCs showed increased clinical symptoms of DSS-induced colitis in mice with a lower number of Tregs." (PMID 33202783, 2020). "In agreement with this notion, one research showed that HIF-1 could exacerbate colitis by promoting inflammatory cell infiltration, and the deletion of HIF-1α in macrophages reduced mortality induced by LPS." (PMID 32848792, 2020). "We found that mannose decreased the number and activation of pro-inflammatory myeloid cells infiltrating colons of DSS-treated mice and to oppose HIF-1α activation, consistent with the role of myeloid HIF-1α activation in promoting DSS-induced colitis progression." (PMID 33311467, 2020). "Here, we hypothesize that miR-155 contributes to intestinal barrier dysfunction in dextran sulfate sodium (DSS)-induced mice colitis by regulating the HIF-1α/TFF-3 axis." (PMID 32713852, 2020). "Moreover, adoptive transfer of these HIF1α KO Treg cells into a murine model of T-cell-mediated colitis demonstrated that the Treg cells were unable to inhibit weight loss or the development of colitis." (PMID 33013855, 2020). "In this study, we demonstrated that HQD could be used to treat DSS-induced colitis through regulation of the Ras-PI3K-Akt-HIF-1α pathway." (PMID 32038240, 2019). "Therefore, HQD alleviated DSS-induced colitis through downregulation of the Ras-PI3K-Akt-HIF-1α pathway, which resulted in inhibition of the NF-κB pathway." (PMID 32038240, 2019). "One should however note that the greater disruptive effect of Co++ on the barrier function of the less-differentiated, 3-day, cell layers — compared to the effect on the more differentiated, 21-day, cell layers — runs counter to the apparent barrier-supportive effect of HIF-1α in colitis models." (PMID 29304733, 2018). "On the other hand, other researchers, using mainly epithelial cell culture and rodent gastrointestinal tissue models have observed that compounds/conditions that increase cellular levels of HIF-1α are supportive of barrier recovery of intestinal cell layers from colitis-like experimental protocols." (PMID 29304733, 2018). "Moreover, a study on the T-cell specific role for HIFs in intestinal inflammation showed that HIF-1α is protective in DSS-induced colitis with increased infiltration of TH1 and TH17 in T-cell specific HIF1α knockout mice." (PMID 29762526, 2018). "Because VHL loss results in constitutive activation of HIF-1α/2α, we wanted to determine whether DSS-induced colitis features that were observed in hMRP8 Vhl KO mice would be reversed in myeloid-specific hMRP8 Hif-1a KO mice." (PMID 29967068, 2018). "We next examined whether the protection from DSS-induced colitis in hMRP8 Hif-1a KO mice would also occur in hMRP8 Hif-2a KO mice." (PMID 29967068, 2018). "Dendritic cell-specific depletion of HIF-1α led to a significantly higher loss of body weight, more severe intestinal inflammation, and increased production of pro-inflammatory cytokines in mice with DSS-induced colitis than in WT mice." (PMID 29762526, 2018).
colitis (continued). "In the present study DSS-induced colitis has been employed in BALB/c mice as an experimental model of gut mucosa inflammation to investigate the effects of HBO2 on HIF-1α, antioxidative enzyme, and proinflammatory cytokine genes during the colonic inflammation." (PMID 27656047, 2016). "Another hint that loss of dendritic HIF-1α may affect the crosstalk between DCs and IECs was the finding that only HIF-1α+f/+f mice exhibited increased levels of thymic stromal lymphopoietin receptor (TSLPR) in DSS colitis." (PMID 26966693, 2016). "In addition, previous studies employing conditional deletion of epithelial HIF-1α or pharmacologic activation of HIF-1α in a murine model of colitis demonstrated a protective role for HIF-1α in colitis." (PMID 27656047, 2016). "Furthermore, conditional knockout of HIF-1α expression in intestinal epithelial cells exacerbated barrier injury and resulted in more severe symptoms in a murine colitis model." (PMID 27002817, 2016). "Consistent with normal levels of Foxp3 in the recovered Tregs, Hif1a-knockout re-established the ability of Dtx1−/− tTregs to repress CD4+CD25− T cell-induced colitis in Rag1−/− mice as determined by colitis score readout, body weight loss and intestinal morphology." (PMID 25695215, 2015). "We hypothesized that TNBS colitis would result in HIF-1α activation, particularly within the epithelium, resulting in increased expression of pro-inflammatory cytokines such as IL-1β and TNF-α, and higher levels of iNOS." (PMID 25926972, 2015). "Therefore, to further confirm this result in vivo, we regulated the level of HIF-1α while simultaneously administering the GPX4 inhibitor RSL3 to DSS-induced acute colitis mice to observe changes in the mice’s general condition, intestinal barrier function, and ferroptosis." (PMID 40691131, 2025). "For example, butyrate enhances IEB function by activating HIF-1α in IEC to upregulate tight junction protein expression, reducing barrier permeability and bacterial translocation, thereby mitigating colonic damage caused by colitis or Clostridioides difficile infection (CDI)." (PMID 38605960, 2024). "Notably, HIF-1a knockout in the same study leads to improvement of acute DSS-colitis." (PMID 36768744, 2023). "In addition, MTA1 facilitated experimental colitis via up-regulating HIF1A." (PMID 35764613, 2022). "Therefore, HIF-1α signaling contributes to colitis resolution." (PMID 36761171, 2022). "In contrast, PPs in mice with DSS colitis contained more regulatory CD11b+ B-cells compared to healthy control mice, which had a protective effect on disease progression and displayed an IL-10-mediated immunosuppressive function that was dependent on hypoxia-inducible factor-a (HIF-1a) expression." (PMID 35163775, 2022). "Therefore, HIF-2α deficiency, but not HIF-1α deficiency, impairs the in vivo suppressive function of tTreg cells that inhibit colitis." (PMID 33024109, 2020). "This phenomenon is particularly relevant in the colonic mucosa, and the effect of HIF-1α in the induction of angiogenesis- and glycolysis-related genes as well as genes involved in mucosal barrier protection has been validated in animal models of colitis and in human-derived colonic tissue." (PMID 31719116, 2019). "Moreover, we note the less impressive contribution of HIF-2α, compared with HIF-1α, to colitis resolution, which may be due to its less dramatic induction under hypoxia in macrophages." (PMID 30455703, 2018). "Preclinical studies in animal models, such as EAE and DSS-induced colitis, have consistently demonstrated the efficacy of targeting metabolic nodes like mTOR, AMPK, HIF-1α, and PKM2 in rebalancing Th17/Treg responses." (PMID 41476956, 2025). "Collectively, it is suggested that enhancing the expression of HIF-1α can upregulate the level of GPX4 to inhibit ferroptosis in colonic epithelial cells, thereby improving colitis in mice." (PMID 40691131, 2025).
colitis (continued). "In summary, this suggests that HIF-1α–mediated ILC1 activation, although detrimental upon acute colitis, prevents against excessive inflammation and fibrosis during chronic intestinal damage." (PMID 38876796, 2024). "In summary, this suggests that HIF-1α–mediated ILC1 activation, although detrimental upon acute colitis, protects against excessive inflammation and fibrosis during chronic intestinal damage." (PMID 38876796, 2024). "In trinitro-benzene-sulfonic acid (TNBS)-induced colitis in rats, glial cell line-derived neurotrophic factor (GDNF) protects enteric neurons from cell death due to metabolic challenges by activating HIF-1α and the REarranged during Transfection (RET) pathway." (PMID 38605960, 2024). "A common feature in both approaches is Hif1a expression, which is related to IBD and DSS-induced colitis." (PMID 37047397, 2023). "Both HIF-1α and HIF-2α are expressed in the intestinal epithelial cells of ulcerative colitis and Crohn’s disease patients and in mouse models of colitis." (PMID 37965556, 2023). "Regarding the APPs’ correlation to mRNA markers, there were moderate positive correlations between CRP levels and Il6, Hif1a, and Il1b1 expression in both trials with DSS-induced colitis." (PMID 37047397, 2023). "Clinical datasets of inflammatory diseases revealed that the gene expression of HIF-1α and NOS2 are correlated in several diseases, like colon inflammation, Crohn’s disease, and mixed osteosarcoma." (PMID 37965321, 2023). "For example, there was significant induction of Traf1, Tnfrsf9, Hif1a, Slc2a1 and Pim1 in TREG clusters in CPI colitis in comparison with TREG clusters in control mice." (PMID 37872166, 2023). "A recent report demonstrated that stabilization of HIF-1α enhanced the production of IL-10 and IL-22 from lamina propria CD4+ T-cells with reduction of inflammatory lesions in DSS-induced mice colitis." (PMID 37201028, 2023). "Certainly, T cell specific deletion of Hif1α significantly downregulates Foxp3 over IL-17 expression, leading to the uncontrolled immune responses in DSS-induced colitis model." (PMID 37809060, 2023). "Results of dual-luciferase reporter gene assay and ChIP assay further revealed that MTA1 activated HIF1A, and subsequently induced AQP4 transcription to up-regulate AQP4 in experimental colitis." (PMID 35764613, 2022). "Herein, we confirmed that 1) hypoxia exerts a barrier protective effect o in a DSS-induced mouse colitis model and VDR is instrumental in it and that 2) the regulatory role of HIF-1α on VDR in protecting the intestinal mucosal barrier." (PMID 35711312, 2022). "Immunohistochemical figures also showed decreased HIF1α and phospho-CaMKII in colons of Lyz2cre/+Piezo1flox/flox compared with Piezo1flox/flox control mice in the DSS-induced colitis." (PMID 36119083, 2022). "So we conducted an alternative experiment of DSS-induced colitis treated with DMOG, which is a cell permeable and competitive inhibitor of HIF-PH, and thus results in HIF-1α stabilization and accmulation in vitro and in vivo." (PMID 35711312, 2022). "Due to the different role of HIF-1α and HIF-2α in ulcerative colitis, the balancing mechanisms of these subunits during therapeutic intervention to treat colitis needs to be further investigated." (PMID 33808042, 2021). "Both HIF-1α and HIF-2α expression are increased in the intestinal epithelium of UC and CD patients and in a mouse model of colitis." (PMID 34502078, 2021). "A candidate of a class of HIF-1α–selective PHD inhibitors, AKB-4924, exhibits protective effects in TNBS-induced colitis." (PMID 33519819, 2020). "Our results here suggest that miR-155 inhibits HIF-1α expression and thereby contributes to the intestinal barrier dysfunction in DSS-induced colitis, and highlights miR-155 antagomir and FG-4497 as potential therapeutic targets to treat human IBD." (PMID 32713852, 2020). "FG-4497, which upregulates HIF-1α expression, elicited protective effects on the intestinal barrier in DSS-induced colitis." (PMID 32713852, 2020).
colitis (continued). "A milder course of colitis was observed with a HIF-1α knockout in myeloid cells and a stronger course of disease with a HIF-1α knockout in DCs, T-cells, and intestinal epithelial cells." (PMID 33202783, 2020). "Given the crucial role of oxygen tension in governing the switch between injury and regeneration in our in vitro model, we examined Hif1α protein levels in atrophic and hypertrophic crypts in DSS-induced colitis." (PMID 31708126, 2019). "In this study, we evaluated the anti-inflammatory effects of HQD against DSS-induced colitis, and showed that these effects occurred through the Ras-PI3K-Akt-HIF-1α pathway." (PMID 32038240, 2019). "The dependency of Tβ4 activity on HIF-1α in lung aspergillosis, and likely in DSS-induced colitis, underpins a more general relationship between the two molecules." (PMID 31719116, 2019). "We investigated the molecular mechanisms of HQD in a murine model of DSS-induced colitis by measuring the expression levels of inflammatory cytokines, receptors, and proteins in the Ras-PI3K-Akt-HIF-1α and NF-κB pathways." (PMID 32038240, 2019). "HQD ameliorates DSS-induced colitis through regulation of the gut microbiota, and suppression of Ras-PI3K-Akt-HIF-1α and NF-κB pathways." (PMID 32038240, 2019). "Knockdown of Hif1α led to the suppression of apoptosis and inflammation in the DSS-induced murine colitis model." (PMID 29636643, 2018). "We add to these findings by demonstrating that myeloid HIF-1α and HIF-2α are crucial to resolve acute colitis." (PMID 30455703, 2018). "However, there is more to the colitis state than simply a less-differentiated epithelial layer, and these other factors (inflammatory mediators, altered vascularization, etc.)could play significant roles in why HIF-1α could be barrier-supportive here." (PMID 29304733, 2018). "This was confirmed in the current study by HypoxyprobeTM-1 staining in combination with HIF-1α and HIF-2α detection in colon tissue after induction of experimental colitis." (PMID 29261815, 2017). "In HFD animals, the exercise significantly accelerated the healing of colitis, raised the plasma levels of IL-6 and irisin, downregulated the expression of IL-1β, TNF-α, and Hif1α, and significantly decreased the plasma IL-1β, TNF α, TWEAK, and leptin levels." (PMID 25684862, 2015). "Hyperbaric oxygen acts diminishing hypoxia (and HIF-1α), consequently decreasing cytokine expression, NO production, COX-2 and neutrophil infiltration, resulting in less damage e amelioration of colitis." (PMID 25926972, 2015). "HIF1α expression in the colon mucosa is protective in the trinitrobenzene sulfonic acid (TNBS) and oxazalone models of murine colitis." (PMID 26183215, 2015). "We demonstrated that HIF-1α was increased both at the mRNA and protein levels in IBD mucosa, in an animal model of colitis and in IBD-EC cells." (PMID 23638125, 2013). "This potentially protective role for MAIT cells in pathological contexts in the gut is also supported by the finding that, in a mouse model of colitis, activated MAIT cells expressed tissue repair genes and secreted barrier-promoting factors, such as hypoxia-inducible factor 1 subunit alpha (HIF1A)." (PMID 40607421, 2025). "HIF-1α stabilization by the PHD inhibitor roxadustat effectively enhanced glycolysis, leading to increased IgA production and reduced colonic inflammation in DSS-induced colitis." (PMID 39543372, 2025). "However, disruption of von Hipple Lindau in the gut epithelium leads to stabilization of both HIF-1α and HIF-2α, with the proinflammatory effects of HIF-2α being dominant in the colitis model." (PMID 39585307, 2024). "For example, in a colitis mouse model, the absence of HIF-1α in intestinal DCs exacerbated colitis symptoms." (PMID 38933270, 2024). "Deletion of HIF-1α in mice intestine epithelial cells showed that the absence of HIF-1α caused more severe 2,4,6-trinitrobenzene sulfonic acid (TNBS)-induced colitis, while the constitutive HIF-1α activation was protective." (PMID 37201028, 2023).
colitis (continued). "The mice lacking HIF-1α in intestine epithelial cells were more sensitive to bacterial toxin with a more severe colitis phenotype as compared to the control mice." (PMID 37201028, 2023). "HIF-1α activation and expression is increased in IBD patients and animal models and suppressing HIF-1α activation through vitamin D receptor signaling ameliorated TNBS- and DSS-induced colitis." (PMID 36232412, 2022). "In mice with colitis, AKB-4924, an HIF-1α activator, enhanced intestinal mucosal barrier function, but no protective effect on the intestinal mucosa was observed in HIF-1α- deficient mice, indicating that HIF-1α in the intestinal mucosa is a target of AKB-4924-mediated protection." (PMID 35576220, 2022). "It is also noteworthy that an existing study identified that the activation of HIF1A in myeloid cells could facilitate dextran sulfate sodium (DSS)-induced colitis development in mice, which is the basis for experimental colitis." (PMID 35764613, 2022). "Furthermore, another vital discovery was that HIF1A induced transcription of AQP4, which exacerbated the habitual occurrence of experimental colitis." (PMID 35764613, 2022). "Altogether, MTA1 may promote AQP4 transcription by activating HIF1A, thus exacerbating DSS-induced experimental colitis in mice, which provides a novel direction for the treatment of experimental colitis." (PMID 35764613, 2022). "First, experimental colitis mouse models were established using dextran sulfate sodium (DSS) and in vitro colonic epithelial cells FHC inflammation models were with lipopolysaccharide (LPS) for determination of MTA1 and HIF1A expressions." (PMID 35764613, 2022). "In contrast, the significant increase in the protein expression of HIF-1α was observed mice fed SD or HFD and subjected to forced treadmill exercise as compared with the corresponding values obtained in sedentary mice with colitis fed either SD or HFD (p < 0.05)." (PMID 31117199, 2019). "Dextran sulphate sodium was used to induce colitis in mice and effect of either free CAPE/PIC or CAPE/PIC loaded albumin nanoparticles treatment was observed on disease development and levels of cellular p65 and HIF-1α." (PMID 30430451, 2019). "Our findings suggest that myeloid AhR is not likely a major contributor to colitis resolution, as disruption of HIF-1α and HIF-2α signaling accounts for the majority of ARNT-dependent effects in our model." (PMID 30455703, 2018). "All of these may be attributed to the improving effect of QCS on vascular endothelial barrier function by regulating the VEGF/HIF-1α signaling pathway, and therefore QCS could serve as alternative medicine for patients suffering from colitis." (PMID 30429788, 2018). "Overall, these data indicate that ARNT depletion disrupts both HIF-1α and HIF-2α transcriptional activity in myeloid cells, offering an excellent opportunity to study myeloid pan-HIF inhibition in multiple disease models, including colitis." (PMID 30455703, 2018). "A similar aggravation in inflammatory damage was seen in C. difficile toxin-induced colitis in mice lacking intestinal epithelial HIF-1α." (PMID 27002817, 2016). "DSS-induced colitis resulted in significant upregulation of HIF-1α gene in colonic mucosa (P = 0.008 for DSS group compared to CTRL), and the HBO2 treatment further increased HIF-1α mRNA expression in the DSS + HBO2 group (P = 0.028 compared to CTRL)." (PMID 27656047, 2016). "Finally, we evaluated expression of HIF-1α and ADORA2B in intestinal mucosa from a rat animal TNBS-induced colitis model and evaluated the effect of 5-ASA." (PMID 23638125, 2013). "Moreover, it has been demonstrated in studies of two HIF‐α isoform double knockout mouse models of acute colitis that HIF‐1α and HIF‐2α in macrophages play opposite roles in acute colitis, suggesting that the relevant expression of HIF‐2α should have an anti‐inflammatory effect." (PMID 41477219, 2025).